ULK2 (unc-51 like autophagy activating kinase 2)
Description:
Serine/threonine-protein kinase involved in autophagy in response to starvation. Acts upstream of phosphatidylinositol 3-kinase PIK3C3 to regulate the formation of autophagophores, the precursors of autophagosomes. Part of regulatory feedback loops in autophagy: acts both as a downstream effector and a negative regulator of mammalian target of rapamycin complex 1 (mTORC1) via interaction with RPTOR. Activated via phosphorylation by AMPK, also acts as a negative regulator of AMPK through phosphorylation of the AMPK subunits PRKAA1, PRKAB2 and PRKAG1. May phosphorylate ATG13/KIAA0652, FRS2, FRS3 and RPTOR; however such data need additional evidences. Not involved in ammonia-induced autophagy or in autophagic response of cerebellar granule neurons (CGN) to low potassium concentration. Plays a role early in neuronal differentiation and is required for granule cell axon formation: may govern axon formation via Ras-like GTPase signaling and through regulation of the Rab5-mediated endocytic pathways within developing axons.
Synonyms: KIAA0623; Unc51.2; ATG1B
Tractability: Small molecule: a structure with a bound ligand is known; a high-quality ligand is known; it belongs to a druggable protein family. Antibody: UniProt places it where antibodies can reach, with high confidence. PROTAC: its protein half-life has been measured; a small molecule that binds it is known.
Target class: Kinase; Other protein kinase group; Other protein kinase ULK family; Enzyme; Protein Kinase
Chemical probes: ULK-101 (high quality)
Safety:
Unwanted effects reported when the protein is acted on. In parentheses: how it was acted on, where the effect was seen, and who reports it.
cardiac arrhythmia (cardiovascular system; source: Lamore et al. (2017))
Gene: Protein-coding gene on chromosome 17 (19,770,829 to 19,867,937, reverse strand). Ensembl gene ENSG00000083290.
Subcellular location: Cytoplasmic vesicle membrane
Gene Ontology:
Molecular function: protein binding; protein serine/threonine kinase activity; ATP binding; protein kinase activity; protein serine kinase activity
Biological process: autophagy; protein autophosphorylation; autophagosome assembly; axon extension; mitophagy; negative regulation of collateral sprouting; piecemeal microautophagy of the nucleus; regulation of autophagy; response to starvation; reticulophagy; axonogenesis; signal transduction
Cellular component: phagophore assembly site membrane; cytosol; phagophore assembly site; cytoplasmic vesicle membrane
Genetic constraint (gnomAD): Loss-of-function variants: 65 observed, 104.33 expected, observed/expected ratio (o/e) 0.62, 90% interval 0.51 to 0.77. The upper end of that interval is the gene's LOEUF score, 0.77, which puts it in group 3 of 6, group 1 being the genes least tolerant of losing a copy. Missense variants: 1,038 observed, 1,189.2 expected, observed/expected ratio (o/e) 0.87, 90% interval 0.83 to 0.92. Synonymous variants: 423 observed, 429.15 expected, observed/expected ratio (o/e) 0.99, 90% interval 0.91 to 1.07.
Homologues: Orthologues: chimpanzee ULK2 (99% identical), dog ULK2 (95% identical), rat Ulk2 (94% identical), mouse Ulk2 (94% identical), rabbit ULK2 (94% identical), macaque ULK2 (93% identical), guinea pig ULK2 (93% identical), pig ULK2 (84% identical), tropical clawed frog ulk2 (80% identical), zebrafish ulk2 (74% identical), Drosophila melanogaster Atg1 (33% identical), Caenorhabditis elegans unc-51 (30% identical). Paralogues in human: ULK1 (53% identical), ULK3 (15% identical).
Diseases named in the same sentence as ULK2 in open-access papers:
ULK2 is named in the same sentence as 51 diseases in open-access papers, as found by Europe PMC text mining. Sharing a sentence is not in itself a finding about the gene and the disease. The quoted sentences say what the papers report.
prostate carcinoma (9 papers, 2018 to 2024). A carcinoma that arises from epithelial cells of the prostate gland. "Unc-51 like autophagy activating kinase 2 (ULK2), a key serine/threonine protein kinase, is pivotal in the initiation of autophagy in various cancers, including gastric cancer, lung adenocarcinoma and prostate cancer." (PMID 38952983, 2024). "In prostate cancer cells, miR-26b inhibited autophagy through targeting ULK2." (PMID 39803361, 2023). "Furthermore, other upstream mediators of autophagy including ATG4B, ATG4D, ULK1 and ULK2 are regulated by AR leading to prostate cancer progression." (PMID 35317831, 2022). "Moreover, miR-26b inhibits prostate cancer by targeting ULK2 cell autophagy." (PMID 36388165, 2022). "Finally, ULK2 is an autophagy regulator overexpressed in prostate cancer cells." (PMID 30194301, 2018). "This miRNA downregulates the expression level of ULK2 by binding to its 3′-UTR to suppress autophagy, leading to prostate cancer progression impairment." (PMID 35317831, 2022). "In prostate cancer cells, miR-26b can inhibit autophagy by targeting ULK2, while ULK2 is found not essential for autophagy induction in adult hippocampal neural stem cells following insulin withdrawal." (PMID 36387235, 2022).
breast carcinoma (5 papers, 2022 to 2026). "In a previous study, chidamide treatments were found to stimulate cell apoptosis by promoting ULK2-mediated autophagy and increasing sensitivity to doxorubicin in breast cancer." (PMID 38594722, 2024). "ULK2 is involved in the autophagy process by promoting the phosphorylation level of downstream proteins, and ULK2 expression is significantly upregulatedin breast cancer and, hepatocellular and esophageal carcinomas." (PMID 39935706, 2024). "And two target genes (ULK2 and RPL36) were significantly positively correlated with LRRC75A-AS1 expression in breast cancer." (PMID 35145966, 2022).
glioma (5 papers, 2020 to 2024). A benign or malignant brain and spinal cord tumor that arises from glial cells (astrocytes, oligodendrocytes, ependymal cells). "We found significant differences in the expression levels of ADD2, CTC1, SRCIN1, RORA, and ULK2 genes in gliomas of different grades, excluding VPS4A." (PMID 39698112, 2024). "In a study demonstrated that hyper-methylation of ULK2 promoter was detected by bisulfite sequencing in glioma cell lines." (PMID 33773561, 2021). "Ectopic expression of ULK2 reduces Ras-induced transformation of astrocytes, showing an inhibitory role of autophagy in glioma transformation." (PMID 32260050, 2020). "Unc-51, like autophagy activating kinase 2 (ULK2), an inducer of autophagy, is hypermethylated and its expression is reduced in glioma." (PMID 32260050, 2020). "Studies have suggested that low expression of ULK2 might be associated with its promoter hypermethylation, causing autophagy by ULK1/ULK2 for glioma progression." (PMID 39348350, 2024). "While correlation analysis identified a strong positive correlation between ULK2 and UVRAG, PTEN, miR-7, and miR-100 in low-grade glioma, unveiling distinctive molecular signatures unique to our study." (PMID 39348350, 2024). "In high-grade glioma, increased expression of AKT and miR-21, coupled with reduced ULK2 and LC3 expression was distinctly observed." (PMID 39348350, 2024). "Similarly, disease-free survival was found to be longer in patients with glioma with high expression of ADD2, CTC1, SRCIN1, RORA, VPS4A, and ULK2 than in those with low expression." (PMID 39698112, 2024). "In 39 glioma cases, we assessed the protein expression of autophagy markers LC3B, SQSTM1/p62, and DRAM by immunohistochemistry (IHC) and the mRNA expression of the autophagy genes PTEN, PI3K, AKT, mTOR, ULK1, ULK2, UVRAG, Beclin 1, and VPS34 using RT-qPCR." (PMID 38203743, 2024). "Furthermore, survival analysis revealed that patients with glioma with high expression of ADD2, CTC1, SRCIN1, VPS4A, ULK2, excluding RORA, had a longer overall survival than those with low expression." (PMID 39698112, 2024). "Considering that AKT, ULK2, LC3, and miR-21 expressions were significantly correlated with glioma grade, we hypothesized that these genes might affect the survival/cancer prognosis of the patients." (PMID 39348350, 2024). "The low ULK2, UVRAG, and miR-374 expression group exhibited significantly poor overall survival in glioma, while miR-21 over-expression indicated a poor prognosis in glioma patients, validating it in our population." (PMID 39348350, 2024). "In grade 3 gliomas, a significant, strong, positive correlation was observed between PI3K and mTOR, ULK2, UVRAG; mTOR and PTEN; PTEN and m-TOR, ULK 2, UVRAG; mTOR and PI3K, PTEN; ULK1 and ULK2, UVRAG; ULK 2 and PI3K, PTEN, ULK 1, UVRAG, VPS34; UVRAG and PI3K, PTEN, ULK1, ULK2, VPS34." (PMID 38203743, 2024).
glioblastoma (4 papers, 2020 to 2024). The most malignant astrocytic tumor (WHO grade IV). "ULK2 overexpression induced autophagy and inhibited astrocyte transformation and tumor growth in glioblastoma." (PMID 34440583, 2021). "Glioblastoma multiforme (GBM), the most lethal human brain tumor, has lower levels of protein markers of autophagy than low-grade astrocytic tumors; in particular, ULK1 and ULK2 levels are significantly lower in GBM patients than in healthy controls." (PMID 38201453, 2023). "In glioblastoma (GBM), low levels of ULK2 transcripts by DNA methylation were reported." (PMID 34440583, 2021). "Additionally, an overexpression of autophagic-related proteins has been observed in a high proportion of glioblastoma patients, with a significant increase of ULK1/ULK2 and TFEB." (PMID 32707662, 2020).
bladder cancer (2 papers, 2021). "While higher expression of APOL1, ATG4B, ITGA3, WDR45, CASP3, and PRKCD is associated with favorable survival in human bladder cancer patients, increased ULK2 and P4HB mRNA levels are negatively correlated to overall survival of bladder cancer patients." (PMID 33925460, 2021). "When tested as individual gene, 9 genes from the 11-ARG signature (APOL1, ATG4B, CASP3, ITGA3, P4HB, PRKCD, ULK2, and WDR45) exhibited a significant association between mRNA expression levels and overall survival of bladder cancer patients." (PMID 33925460, 2021). "ULK2 knockdown inhibited autophagy and apoptosis in bladder cancer cells." (PMID 33925460, 2021). "In bladder cancer cells, UM-UC-3, the AR influences autophagy by regulating ULK2; in presence of an AR knockdown, the mRNA and protein level of ULK2 are up-regulated, but with DHT treatment, the protein expression of ULK2 decreased." (PMID 33919565, 2021).
esophageal carcinoma (2 papers, 2015 to 2024). A primary or metastatic malignant neoplasm involving the esophagus. "Hypermethylation of five autophagy-related genes, BECN-1, ATG16L2, ULK2, BNIP3 and a variant of LC3A, were previously reported respectively in BC, leukemia, astrocytoma, colorectal cancer and esophageal carcinoma and these data demonstrated that this hypermethylation was correlated to tumor grade." (PMID 26474850, 2015).
gastric cancer (2 papers, 2022 to 2024). A primary or metastatic malignant neoplasm involving the stomach. "ULK2 can be silenced by methylation, which may induce epithelial-mesenchymal transition and transformation to poorly differentiated status in a gastric cancer cell line." (PMID 36387235, 2022).
pancreatitis (2 papers, 2019 to 2021). Inflammation of the pancreas. "rs281366 variant in ULK2 gene showed the strongest association with pancreatitis, and interestingly, 14 of the 27 associations were of polymorphisms in this same gene." (PMID 35582721, 2019). "The authors also applied a targeted genotyping approach to test the reproducibility of the association of the ULK2 variant rs281366 and RGS6 variant rs17179470 with the risk of pancreatitis previously reported by the same group but the results were not significant." (PMID 35582721, 2019).
psoriasis (2 papers, 2017 to 2018). An autoimmune condition characterized by red, well-delineated plaques with silvery scales that are usually on the extensor surfaces and scalp. "Degradation of BCL10 by ULK2 requires phosphorylation of CARMA2sh, and is prevented by several psoriasis-linked CARMA2sh mutations." (PMID 28230860, 2017). "Remarkably, CARMA2sh mutants associated with psoriasis escape ULK2 inhibition." (PMID 28230860, 2017). "Even more importantly, two of the most recurrent psoriasis-linked mutants, CARMA2shE138A and CARMA2shE142G, which are both stronger activators of NF-κB compared to wt CARMA2sh,6, 7, 8 were only slightly affected by ULK2 expression." (PMID 28230860, 2017). "We also show that at least three CARMA2sh mutants associated with genetic psoriasis fail to promote degradation of BCL10, despite being phosphorylated by ULK2." (PMID 28230860, 2017). "Also, together with the evidences shown before, these experiments indicate that ULK2 negatively regulates this pathway, whereas the two psoriasis-linked CARMA2sh mutants tested escape such a negative control." (PMID 28230860, 2017). "Altogether, these data indicate that ULK2-mediated lysosomal degradation of BCL10 represents an intrinsic homeostatic mechanism that restricts NF-κB signaling in keratinocytes, and the psoriasis-linked CARMA2sh mutants we tested failed to promote such a constraining mechanism." (PMID 28230860, 2017).
cervical cancer (1 paper, 2021). A primary or metastatic malignant neoplasm involving the cervix. "In addition, our analysis about genomic alterations and methylation of ATG5 showed the concomitant occurrence of ATG5 mutation and ULK2 mutation and indicated that methylation sites of ATG5 could also serve as prognosis predictors in cervical cancer patients." (PMID 34901004, 2021).
colon cancer (1 paper, 2020). "FuSiOn identified ten kinases (BMP2K, DCLK3, LIMK2, MAP2K5/MEK5, MAP3K3/MEKK3, ROS1, SIK2, TAOK2, ULK1, and ULK2) whose depletion mimicked the phenotypic effect of p62 depletion in HCT116 colon cancer cells." (PMID 33101709, 2020).
diabetes (1 paper, 2019). "Out of these 15 predicted genes, we selected 4 target genes (IGF-1, SLC2a-12, EIF-4e, and ULK-2) based on the available literature related to myocardial function and/or diabetes for experimental validation." (PMID 30823517, 2019).
gastroenteritis (1 paper, 2024). An inflammatory disorder that affects the upper and lower gastrointestinal tract. "ULK2 was associated with PD in UK Biobank (332, P = 3.5 × 10−2) and noninfectious gastroenteritis and “Hemorrhage of gastrointestinal tract” in BioMe (P = 1.38 × 10−2 and 3.12 × 10−2)." (PMID 38741190, 2024).
inflammatory bowel disease (1 paper, 2020). A spectrum of small and large bowel inflammatory diseases of unknown etiology. "Unravelling differences between ULK1 and ULK2 could lead to a better understanding of how ULK-type specific dysregulation affects autophagy and other cellular processes that have been implicated in diseases such as inflammatory bowel disease and cancer." (PMID 32616830, 2020).
myopia (1 paper, 2026). "Our meta-analysis identified seven novel suggestive loci associated with myopia progression, including FSTL5 on 4q32.2, SMARCA2 on 9p24.3, CCDC3 on 10p13, GALNT6/ACVR1B on 12q13.13, CRY1 on 12q23.3, ULK2 on 17p11.2, and MYL4/EFCAB13-DT on 17q21.32." (PMID 42094695, 2026).
ovarian carcinoma (1 paper, 2024). A malignant neoplasm originating from the surface ovarian epithelium. "Based on the collective findings, we propose that ULK2 functions as a tumor suppressor gene in ovarian cancer and its high expression is associated with more favorable prognosis for patients." (PMID 38952983, 2024). "Subsequently, the association between ULK2 and survival outcomes of ovarian cancer patients was examined." (PMID 38952983, 2024). "RNA sequencing analysis revealed a potential regulatory role of ULK2 in the insulin signaling pathway through upregulation of insulin-like growth factor binding protein-3 (IGFBP3) in ovarian cancer cells." (PMID 38952983, 2024). "The transwell assay revealed substantial inhibition of migration and invasion of ovarian cancer cells overexpressing ULK2." (PMID 38952983, 2024). "In summary, the collective data indicated that ULK2 acted as a tumor suppressor in ovarian cancer by upregulating the expression of IGFBP3." (PMID 38952983, 2024). "Accordingly, we propose that ULK2 suppresses the migration and growth of ovarian cancer cells through inhibition of the IGFBP3-mediated insulin signaling pathway." (PMID 38952983, 2024). "Analysis of the GEPIA database revealed that ULK2 exhibited low expression in advanced ovarian cancer and relatively high levels in early-stage cancer." (PMID 38952983, 2024). "This study aimed to explore the expression and functional role of Unc-51 like autophagy activating kinase 2 (ULK2) in the progression of ovarian cancer." (PMID 38952983, 2024). "ULK2 expression patterns in ovarian cancer tissues as well as benign tumor control samples obtained from our institution were evaluated using immunohistochemistry." (PMID 38952983, 2024). "The results revealed low H-Score and positive expression rate of ULK2 in advanced ovarian cancer compared to early-stage cancer." (PMID 38952983, 2024). "The study aimed to explore the expression and functional significance of ULK2 in the progression of ovarian cancer as well as mechanisms other than autophagy regulation." (PMID 38952983, 2024). "Evaluation of the survival period of 557 ovarian cancer patients from the TCGA database indicated a positive link between ULK2 expression and survival." (PMID 38952983, 2024). "In subsequent in vitro experiments, ULK2 negatively regulated proliferation, motility, and invasion of ovarian cancer cells." (PMID 38952983, 2024). "Our collective findings suggest that ULK2 can diminish ovarian cancer cell proliferation and migration through inducing an increase in IGFBP3 expression." (PMID 38952983, 2024). "In summary, our current research exploratively discovered that ULK2 suppressed cell migration and invasion of ovarian cancer via inhibition of the insulin signaling pathway by promoting upregulation of IGFBP3." (PMID 38952983, 2024). "Our results clearly demonstrate that ULK2 markedly suppresses cell invasion and motility in ovarian cancer." (PMID 38952983, 2024). "The findings indicated low expression of ULK2 in ovarian cancer tissues and high expression in benign ovarian cysts or tumors." (PMID 38952983, 2024). "Our study underscores the potential utility of ULK2 as a valuable prognostic marker for ovarian cancer." (PMID 38952983, 2024). "The CCK-8 assay indicated that the increased ULK2 levels suppressed the proliferation of ovarian cancer cells in both OVCA433 and HEY A8 cell lines." (PMID 38952983, 2024). "Initially, analysis of patient samples revealed significant downregulation of ULK2 in ovarian cancer tissues relative to benign ovarian tumor samples." (PMID 38952983, 2024). "Additionally, Western blot analysis revealed a significant decrease in ULK2 expression in the ovarian cancer cell lines OVCA433 and HEYA8." (PMID 38952983, 2024). "However, further studies, particularly in vivo experiments, are necessary to fully uncover the impact of ULK2 on the progression of ovarian cancer." (PMID 38952983, 2024).